ALB (albumin)
Diseases named in the same sentence as ALB in open-access papers (continued):
Sharing a sentence is not in itself a finding about the gene and the disease.
infection (continued). "On the other hand, lower albumin levels may have been due to the increased rate of transcapillary leak of albumin into the interstitial fluid associated with infection." (PMID 28421202, 2017). "In binary regression analysis, higher creatinine concentration (odds ratio 1.004, 95% confidence interval 1.001–1.007, p = 0.016) and lower albumin concentration (odds ratio 0.953, 95% confidence interval 0.916–0.991, p = 0.016) were the only factors independently associated with infection." (PMID 28389732, 2017). "Biologically, a low albumin level was strongly associated with the risk of infection." (PMID 27218256, 2016). "Further studies are needed to assess whether low albumin level is a risk factor for infection by itself (e.g., by being associated with a higher free glucocorticoid fraction) or whether it reflects other underlying causes of general debilitation." (PMID 27218256, 2016). "In addition, it was found by univariate analysis that HCV genotypes 2a/3a infection, younger age, shorter PT, higher level of ALB and CHO were associated with higher SVR rates." (PMID 25337144, 2014). "Therefore, intensive management of risk factors (high BMI and low albumin) and prompt recognition of infection is therefore recommended for CAPD patients with DN to improve quality of life." (PMID 23585903, 2013). "In mammals reduced circulating serum albumin levels correlates with increased susceptibility to infection which may also be the case in fish." (PMID 20602791, 2010). "Creatinine and related renal markers may influence anesthetic choice, fluid and electrolyte balance, and drug dosing while glucose levels can inform infection risk and wound-healing complications, and albumin reflects nutritional reserve and hemostatic balance." (PMID 41227080, 2025). "Similarly, albumin (ALB) synthesized by liver cells not only reflects the body’s nutritional status but is also closely associated with inflammation, with its level decreasing as infection worsens." (PMID 39026204, 2024). "The low level of ALB reflects that the patient’s liver function and nutritional status are poor, the detoxification function of the body is reduced, and the ability to resist pathogenic bacteria is significantly reduced, which makes the patient prone to infection." (PMID 37704966, 2023). "Additionally, these data show the tremendous increase in infection risk with low albumin." (PMID 35119125, 2022). "It was stated previously that the infection with B. gibsoni in dogs causes marked alterations in serum biochemistry parameters, including those related to the protein profile that were characterized by lower concentrations of albumin and higher proportion of γ-globulins with low A/G ratio." (PMID 35327106, 2022). "Albumin could be a good prognostic marker because it is a global indicator of individual susceptibility, bringing together the influence of comorbidities, anti-inflammatory reactions to infection, markers of systemic inflammation, and nutritional status." (PMID 35740416, 2022). "If low serum albumin levels can be shown to directly affect innate immunity and antimicrobial defense, associations with infectious diseases might also lead to the identification of low albumin mass as culprit, causally contributing to both acquisition and development of complications of infections." (PMID 33925831, 2021). "However, the absence of significant changes in albumin/globulin ratio at 3 and 4 dpi/dpe in chickens, despite hyperproteinemia, might be due to decreased albumin resulting from hemorrhages and anorexia caused by vvIBDV infection." (PMID 34150893, 2021). "Therefore, low serum albumin increases the susceptibility to infection complications." (PMID 34566849, 2021).
infection (continued). "When compared to infections with B. canis, characteristic alterations in the serum protein associated with B. gibsoni infection in dogs include significantly higher total serum proteins and γ-globulins, while the relative concentrations of albumin and A/G ratio are markedly significantly lower." (PMID 33144631, 2020). "Reduction in serum albumin level may suggest infection or continuous loss of albumin." (PMID 29402248, 2018). "First, this was a retrospective study and the causal and effect relationships between albumin, nPCR and all-cause, CV, and infection related mortality need further prospective study to see whether improvement of albumin and nPCR can improve mortality in HD patients." (PMID 27752119, 2016). "However, nab-PTX contains human albumin, suggesting a potential risk of infection." (PMID 27595901, 2016). "Furthermore, after one year of observation, patients in the lowest tertile of baseline serum NGAL levels were at a significant risk to experience marked decline in serum albumin levels and showed an increased tendency to develop severe infection, as compared to the middle and highest tertiles." (PMID 26161663, 2015). "Low serum albumin content may suggest infection or continuous loss of albumin." (PMID 24386634, 2013). "Cardiovascular events (35.1% vs. 19.7%, p = 0.001) and infection-related hospitalizations (42.3% vs. 25.4%, p < 0.001) were significantly more common in the low-albumin group." (PMID 41517580, 2026). "Conversely, a higher postoperative albumin level (OR = 0.87, 95% CI: 0.80-0.94, P < .001) served as an independent protective factor against infection." (PMID 42116368, 2026). "Data on demographics, infection sites, pathogens, laboratory markers (platelets, albumin, creatinine, lactate), organ dysfunction scores (PCIS), and clinical outcomes (mechanical ventilation, CRRT, MODS, DIC, mortality) were collected." (PMID 41710800, 2026). "New evidence indicates that biomarkers such as cortisol, IL-6, glucose, and albumin serve as predictors of postoperative complications, including infection, impaired wound healing, and increased morbidity." (PMID 41589142, 2025). "The C-reactive protein(CRP)/albumin ratio represents a combination of the infection level andnutritional status." (PMID 40622101, 2025). "The virus stock solution was adjusted to the desired multiplicity of infection (MOI) in phosphate-buffered saline (PBS) supplemented with 0.2% bovine serum albumin (BSA), 1 mM MgCl2, 0.9 mM CaCl2, 100 U/mL penicillin and 0.1 mg/mL streptomycin." (PMID 40295791, 2025). "(J) Dual immunostaining of Ag85B (red) and albumin (green) shows distinct signals of Mtb within the isolated hepatocytes from infected mice at 8 weeks post-infection." (PMID 41358489, 2025). "Neutrophil percentage-to-albumin ratio (NPAR) emerged as a new predictive marker for poor infection prognosis, which proved to be more accurate than albumin or neutrophil percentage alone." (PMID 41209009, 2025). "The neutrophil-to-albumin ratio (NPAR) has been identified as a novel marker for systemic infection and inflammation in humans." (PMID 40697910, 2025). "The presumed site of infection varied, with more patients in the albumin group admitted for an abdominal source (48% vs. 27%) and fewer for a genitourinary infection (2% vs. 15%)." (PMID 40386509, 2025). "Initial therapy should be bundled and time-sensitive: remove nephrotoxins, treat infection and initiate albumin plus a vasoconstrictor." (PMID 41301868, 2025). "Our findings revealed that patients with serum albumin levels below 3.5 g/dL had a markedly higher rate of complications, including surgical site infections, anastomotic leaks, wound dehiscence and delayed wound healing." (PMID 40698225, 2025). "The objective of this work is to investigate the predictive value of the neutrophil-to-lymphocyte ratio (NLR) combined with the C-reactive protein/albumin (CRP/ALB) ratio for postoperative infections in patients undergoing spinal surgery." (PMID 41019129, 2025).
infection (continued). "Management should be early, bundled and goal-directed: stop nephrotoxins, treat infection and initiate albumin plus a vasoconstrictor (terlipressin where available; norepinephrine in the ICU; midodrine/octreotide when other options are not feasible)." (PMID 41301868, 2025). "Low serum albumin levels are crucial biomarkers of inflammation severity and infection complications." (PMID 41001124, 2025). "Data on serum albumin, inflammatory markers and catheter dwell time were unavailable, despite being known predictors of infection." (PMID 41373275, 2025). "The neutrophil-to-albumin ratio (NPAR), a blood biomarker reflecting the ratio of neutrophils to serum albumin levels, is an indicator of inflammatory status, infection, and nutritional state." (PMID 40115342, 2025). "Typical SoC treatment includes antibiotics to target the infection, fluids to manage septic shock symptoms, and occasionally albumin (ALB) serum to boost the immune system." (PMID 41626967, 2025). "During the infection episodes, however, the albumin concentration dropped to values below the normal range." (PMID 40732135, 2025). "In particular, albumin levels are known to be influenced by inflammation, infection, and hepatic function, in addition to the nutritional status." (PMID 40870441, 2025). "The present findings show that nephrectomy significantly decreases the number of required albumin infusions, infections, and hospitalizations in patients with CNS secondary to NPHS1 mutations." (PMID 40266336, 2025). "Effect of Salmonella Typhimurium infection on serum albumin (g/dL) at different days post-infection." (PMID 41568335, 2025). "The rapid decline in serum albumin levels during the acute phase of infection reflects the severity of the systemic inflammatory response and serves as a widely used indicator of poor prognosis in critical care settings." (PMID 40046064, 2025). "For example, for patients with high NPAR, proactive anti-infection treatment, nutritional support, and organ function protection measures can be taken to reduce inflammatory responses and improve albumin levels, thereby enhancing patient prognosis." (PMID 41036272, 2025). "Regarding the results of the serum proteins and kidney function, the combination treatment (LG + SP) higher serum total protein, albumin, and globulin levels before infection." (PMID 40730597, 2025). "Clinical parameters including albumin infusion requirements, infections, hospitalizations, growth, and survival rates were analyzed in the Nx and non-Nx groups." (PMID 40266336, 2025). "Compared to the non-infection group, patients in the infection group exhibited a significant decrease in albumin levels and a notable increase in total cholesterol and erythrocyte sedimentation rate levels." (PMID 40125519, 2025). "The patient herein met the typical triad, and the supporting features included a history of infection and albumin-cytologic dissociation in CSF." (PMID 40040715, 2025). "In recent years, serum CD64, VEGF, SDF-1, NLR, and the CRP/ALB ratio have been increasingly recognized for their potential in early infection diagnosis." (PMID 41019129, 2025). "At 12 months post-nephrectomy the number of albumin infusions required, infections, and hospitalizations decreased significantly in the Nx group, as compared to the pre-nephrectomy period (p = 0.001, p = 0.027, and p = 0.004, respectively)." (PMID 40266336, 2025). "As infection control progresses, the host shifts from an “acute-phase response” to resumption of constitutive protein synthesis, including albumin." (PMID 41150817, 2025). "Albumin reflects nutritional and hepatic status and declines during inflammation, infection, and organ dysfunction." (PMID 40873797, 2025). "Infiltration of immune cells from nasal tissue to the site of infection transports significant amounts of albumin and calcium, which are present in the extracellular fluid." (PMID 40135913, 2025).
infection (continued). "Elevated D-dimer levels have been linked to increased coagulation and potential microvascular injury, while higher procalcitonin and C-reactive protein, together with lower albumin levels, indicate systemic inflammation and possible infection." (PMID 41551652, 2025). "The present findings show that the number of albumin infusions, infections, and hospitalizations decreased significantly after nephrectomy, as compared to the pre-nephrectomy period." (PMID 40266336, 2025). "There were notable alterations in the biochemical markers, with total protein, albumin, and globulin levels fluctuating with the severity of infection." (PMID 40017589, 2025). "The liver is a main site for albumin production in fish, and infection with salmon louse copepodids decreases plasma albumin in sea trout." (PMID 41311413, 2025). "After infection, compared to the same group prior to infection, all groups’ blood protein and kidney function test levels dropped, except albumin in the SP group." (PMID 40730597, 2025). "And intact innate and adaptive immune responses rely on albumin, PWH also provide a medium for bacteria to multiply, which unfortunately results in an increased risk of surgical site infection." (PMID 39671379, 2024). "Multivariate logistic regression analysis showed that infection, psychiatric symptoms, serum sodium, albumin, neutrophil-lymphocyte ratio (NLR) and eosinophil-lymphocyte ratio (ELR) were independent risk factors for AC." (PMID 39741879, 2024). "In the current study, we noted that UGT1A1, ALB, and COX6A1 in the late-infection-stage PPI are associated with liver homeostasis." (PMID 39625960, 2024). "Plasma glucose concentration decreased during mid-infection; however, total protein, albumin, globulin, and cholesterol concentration increased at 14 DPI." (PMID 39457937, 2024). "Extensive research revealed that the low level of albumin reduced the immune level of the body, and the anti-infection ability was weak." (PMID 39698463, 2024). "Mice with human albumin levels exceeding 1000 μg/mL at 10–12 weeks post-human hepatocyte transplantation were selected for mock infection (n = 1), HBV mono-infection (n = 3), and HBV-HDV superinfection (n = 3)." (PMID 38687692, 2024). "On comparative analysis of both groups; infection, Meld score, low albumin, and raised total bilirubin showed significant P-value (<0.05)." (PMID 38196479, 2024). "Our study also highlighted infection originated from abdomen and serum albumin as novel predictors of hypovitaminosis C." (PMID 38429378, 2024). "Other studies identified MELD score, lactates, infection, albumin, and CRP and CRP/albumin ratio as independent predictors of in-hospital mortality." (PMID 39594174, 2024). "Lower albumin levels lead to insufficient synthesis of immunoglobulins, reducing patients’ ability to fight infection." (PMID 39868370, 2024). "Values of AST, ALT, GGT, Total bilirubin, and Albumin showed a significant increase, with all the immunosuppressed goats dying on the 4th and 7th days post-infection, while four out of seven immunocompetent goats died on between 6-8th days." (PMID 39621802, 2024). "This review aimed to analyse the impact of pre-operative serum albumin on the incidence of surgical site infections in adult patients undergoing surgery for a hip fracture." (PMID 38817798, 2024). "Low serum albumin levels can impair vascular integrity and promote bacterial invasion, exacerbating infection severity." (PMID 39113089, 2024). "Low serum albumin levels are a marker for infection because they can directly affect the body’s ability to fight infections." (PMID 38561807, 2024). "Dehydration can lead to elevated albumin levels, while in pathological states such as infection or chronic inflammation, the activation of the host inflammatory response can stimulate immunoglobulin production, leading to an increase in globulin levels." (PMID 39061596, 2024).
infection (continued). "At the same time, we give attention to blood pressure, electrocardiogram, albumin, calcium, potassium, acidosis, coagulopathy, anti-infection, and protection of vital organs is essential for successful retransplant outcomes." (PMID 38181254, 2024). "Patients who had a relative increase or decrease in hematocrit level of ≥ 10% during the first 5 days of illness, white blood cell count ≥ 4 × 109/L, platelet count < 100 × 109/L, and serum albumin < 35 g/L had higher odds of severe infection." (PMID 39039529, 2024). "It has been reported that the orosomucoid level increases several-fold during infection or trauma in order to reduce the transvascular leakage of albumin." (PMID 38275815, 2024). "Our study findings also confirmed this result and highlighted that an abnormal albumin level below 35 g/L in the first 5 days of illness increased the probability of severe infection." (PMID 39039529, 2024). "Postoperatively, the patient received symptomatic supportive therapy, including anti‐infection treatment, hemostasis, albumin infusion, and abdominal drainage." (PMID 39559283, 2024). "In this study, we conducted a comprehensive analysis of the clinical characteristics of patients with GIAI and identified infection, psychiatric symptoms, serum sodium level, albumin level, NLR, and ELR as independent predictors of AC in these patients." (PMID 39741879, 2024). "The odds of infection were reduced by 7% with each g/dl of serum albumin increment (AOR = 0.93, 95% CI: 0.87, 0.988)." (PMID 38987746, 2024). "Larger PCT in death cases compared to normal and long infection, as well as lower ALB, reveals a state of severe infection from which recovery is difficult." (PMID 38752789, 2024). "Globulin is a serum protein secreted by the liver and elevated in infective and inflammatory pathology, where the albumin level decreases with acute inflammation and infection." (PMID 39493345, 2024). "In the systematic covariate analysis, seven rounds of univariate forward inclusion yielded six covariate effects that were added to the base model: study on CL, infection status on V1, albumin on V23, and body surface area (BSA) on CL, V1, and V23." (PMID 38014945, 2023). "In this study, leukocyte count and C-reactive protein on the first postoperative day were selected as indicators of infection, and hemoglobin and albumin on the first postoperative day were used as biochemical indicators for observation." (PMID 37940888, 2023). "As the severity of frailty increases, the proportion of sodium, potassium, albumin supplementation as well as anti-infection gradually increases." (PMID 38249717, 2023). "The protein recommendations are designed to offset the reductions caused by dialysis, irregularities in protein metabolism, alterations in albumin turnover, heightened breakdown of amino acids, inflammation, and infection." (PMID 37742012, 2023). "IBV infection typically effects the cells of the magnum, leading to thin and watery albumin which ultimately reduces the Haugh unit values." (PMID 38313768, 2023). "Compared with Acinetobacter baumannii single infection, co-infected patients exhibited lower serum albumin and urea nitrogen (P=0.04)." (PMID 37434786, 2023). "The aim of this prospective study is to evaluate the possible prognostic role of the albumin concentration recorded in patients with an infection on arrival in the ED." (PMID 37240554, 2023). "Further, 22 features with statistical differences in univariate analysis were enter into the LASSO regression analysis, and 11 were significantly associated with infection, including GIB, HF, TP, TB, hemoglobin, Na, ALB, PTA, BUN, WBC count, and NLR." (PMID 37704966, 2023). "Following the onset of infection, trauma, and inflammation, storage proteins in the body such as muscles and albumin undergo degradation, leading to the enhanced production of the inflammatory protein CRP (C-reactive protein) to activate the immune response." (PMID 38137581, 2023).